MIR19A (microRNA 19a)
Synonyms: hsa-mir-19a; C13orf25; MIRH1; MIRHG1; MIRN19A; miR-19a; miRNA19A
Gene: MicroRNA gene on chromosome 13 (91,350,891 to 91,350,972, forward strand). Ensembl gene ENSG00000284204.
Gene Ontology:
Biological process: miRNA-mediated post-transcriptional gene silencing
Cellular component: RISC complex
Homologues: Orthologues: chimpanzee ptr-mir-19a (100% identical), guinea pig MIR19A (100% identical), macaque mml-mir-19a (100% identical), pig ssc-mir-19a (100% identical), mouse Mir19a (99% identical), rabbit MIR19A (99% identical), rat Mir19a (98% identical), tropical clawed frog xtr-mir-19a (91% identical), zebrafish dre-mir-19a (88% identical), zebrafish dre-mir-19b (62% identical), tropical clawed frog xtr-mir-19b-2 (61% identical). Paralogues in human: MIR19B1 (62% identical), MIR19B2 (62% identical).
Diseases named in the same sentence as MIR19A in open-access papers:
MIR19A is named in the same sentence as 3 diseases in open-access papers, as found by Europe PMC text mining. Sharing a sentence is not in itself a finding about the gene and the disease.
MIR19A shares sentences with these, for which no sentence is quoted: lung carcinoma (1 paper); neurological diseases (1); tumor (1).